SNORD3C (small nucleolar RNA, C/D box 3C)
Synonyms: U3-3; RNU3-3
Gene: Small nucleolar RNA gene on chromosome 17 (19,189,665 to 19,190,245, reverse strand). Ensembl gene ENSG00000264940.
Gene Ontology:
Biological process: RNA processing
Cellular component: nucleolus
Diseases named in the same sentence as SNORD3C in open-access papers:
SNORD3C is named in the same sentence as 1 disease in open-access papers, as found by Europe PMC text mining. Sharing a sentence is not in itself a finding about the gene and the disease. The quoted sentences say what the papers report.
immune dysfunction (1 paper, 2022). "The dysregulation of U3 small nucleolar ribonucleoproteins genes (SNORD3B-1, SNORD3A, SNORD3B-2, SNORD3C, and SNORD3D) are related to age-related immune dysfunction, G0/G1 to S phase transition, oxidative-/ER-stress (23349890), and pathogenesis of AD." (PMID 35958988, 2022).